GIT1 (GIT ArfGAP 1)
Diseases named in the same sentence as GIT1 in open-access papers (continued):
Sharing a sentence is not in itself a finding about the gene and the disease.
lung cancer (8 papers, 2014 to 2025). A malignant neoplasm involving the lung. "In lung cancer, GIT1 stimulated cancer cell mobility and metastasis by altering the activity of Rac/Cdc4234." (PMID 35318302, 2022). "For example, GIT1 promotes the migration of lung cancer cells through activating the activity of Rac1/Cdc42." (PMID 34663332, 2021). "GIT1 has been demonstrated to be over-expressed in several cancers including hepatocellular carcinoma, colon cancer, lung cancer and melanoma." (PMID 29862012, 2017). "Our results suggest that GIT1-mediated regulation of lung cancer cell motility depends, at least in part, on its ability to modulate Cdc42 and Rac1 activity." (PMID 26462147, 2015). "To elucidate the clinical relevance of GIT1 in lung cancer patients, we first analyzed GIT1 mRNA expression profiles from TCGA database." (PMID 26462147, 2015). "GIT1 expression increased lung cancer cell invasiveness through Rac1/Cdc42 activity and promoted tumor growth and metastasis in vivo." (PMID 26462147, 2015). "In this study we investigated the role of GIT1 in lung cancer by analyzing its immunohistochemical expression in clinical NSCLC patients and its phenotypic impact in vitro and in vivo." (PMID 26462147, 2015). "Similar correlations between GIT1 expression and survival of lung cancer patients were also observed in SurvExpress databases." (PMID 26462147, 2015). "Although correlation between GIT1 and lung cancer cell migration has been observed, the role of GIT1 in NSCLC progression is still elusive." (PMID 26462147, 2015). "Among the 1432 lung cancer patients, lower GIT1 mRNA levels were significantly correlated with longer survival periods." (PMID 26462147, 2015). "Next we examined the Spearman's rho correlation to determine the GIT1 and Rac1/Cdc42 correlation in our lung cancer cohort." (PMID 26462147, 2015). "As such, our study is the first to demonstrate that GIT1 expression might serve as a predictive marker for lung cancer progression." (PMID 26462147, 2015). "We have therefore evaluated whether SNX27 and MYO18A also regulate lung cancer cell motilities through the PIX/GIT1 complex." (PMID 26462147, 2015). "GIT1 expression was also correlated with lung cancer progression in NSCLC." (PMID 26462147, 2015). "To determine whether GIT1 modulates lung cancer cell migration and invasion, we silenced GIT1 in A549 and CL1–5 cells using GIT1-specific lentiviral shRNAs." (PMID 26462147, 2015). "Besides, We also examined the correlation between GIT1 mRNA levels and overall survival among lung cancer patients by using Kaplan-Meier (KM) Plotter, an online meta-analysis-based biomarker assessment tool." (PMID 26462147, 2015). "We then evaluated the functional role of GIT1 on the invasiveness of lung cancer cells." (PMID 26462147, 2015). "Moreover, in our previous study, we found that GIT1 is involved in the regulation of lung cancer cell motility." (PMID 26462147, 2015). "We speculate that GIT1 is a predictive marker for cancer progression in NSCLC and may be a potential therapeutic target for lung cancer patients." (PMID 26462147, 2015).
colon cancer (6 papers, 2015 to 2026). "In conclusion, a small molecule inhibitor that disrupts GIT1's normal interactome is a promising new approach to treating liver and colon cancers." (PMID 41720764, 2026). "Previous studies have found that MAT2B and GIT1 interact and are overexpressed in most human liver cancer and colon cancer specimens." (PMID 30379973, 2018). "GIT1 expression also associated with poor prognosis in multiple cancers, including cervical, breast, OSCC, HCC and colon cancers." (PMID 26462147, 2015). "The up-regulation of GIT1 has recently been reported in oral, cervical, breast, liver and colon cancer." (PMID 26462147, 2015). "For example, it has been shown that methionine adenosyltransferase 2B (MAT2B) and GIT1 form a complex to control cancer cell growth and are overexpressed in most human liver and colon cancer specimens." (PMID 26462147, 2015). "Previous studies have found GIT1 to be overexpressed in many types of metastatic tumors, including oral, cervical, breast, liver and colon cancers." (PMID 26462147, 2015). "Furthermore, the growth of liver and colon cancer is regulated by a signal cascade in which GIT1 activates ERK plus MEK by interacting with MAT2B36." (PMID 35318302, 2022).
osteosarcoma (5 papers, 2020 to 2025). A usually aggressive malignant bone-forming mesenchymal neoplasm, predominantly affecting adolescents and young adults. "Furthermore, we explored the association between GIT1 and lincFOXF1 expression in osteosarcoma tissues, and the results indicated an inverse correlation (R = −0.451, P = 0.002)." (PMID 32945076, 2020). "The impact of GIT1 depletion on microtubule nucleation was significantly less pronounced in glioblastoma cells compared to mouse mast cells or human osteosarcoma cells." (PMID 40176062, 2025). "In osteosarcoma, GIT1 silencing effectively suppresses tumor growth, invasion, and angiogenesis." (PMID 33258389, 2021). "The knockdown of GIT1 in human osteosarcoma cells has shown in vivo and in vitro reduced tumour cell growth, invasion and angiogenesis, which could make GIT1 a potential target in gene therapy." (PMID 34103645, 2021). "To identify the potential downstream target genes related to lincFOXF1 in osteosarcoma, we conducted qRT‐PCR to assess expression of multiple molecules (such as N‐cadherin, Integrin, CD44, ICAM‐1, Vimentin, Fibronectin, GIT1 and FOXF1) in osteosarcoma cells after gain or loss of lincFOXF1 function." (PMID 32945076, 2020). "Moreover, we examined potential target genes related to the lincFOXF1 phenotype in osteosarcoma cells and interestingly found dramatic changes in GIT1 levels after overexpression or silencing of lincFOXF1." (PMID 32945076, 2020). "Moreover, GIT1 expression is inversely correlated with lincFOXF1 in osteosarcoma." (PMID 32945076, 2020). "The present findings indicate that lincFOXF1 is involved in the progression of osteosarcoma through binding with EZH2, further regulating GIT1 expression." (PMID 32945076, 2020).
cervical cancer (4 papers, 2015 to 2021). A primary or metastatic malignant neoplasm involving the cervix. "For example, miR-149 regulated cell proliferation and apoptosis by targeting G-protein-coupled receptor (GPCR)-kinase interacting protein-1 (GIT1) in cervical cancer." (PMID 31889909, 2019).
hepatocellular carcinoma (4 papers, 2017 to 2026). A malignant tumor that arises from hepatocytes. "ARF GTPase protein 1 (GIT1) is a scaffold protein that is overexpressed in hepatocellular carcinoma (HCC) and colorectal cancer (CRC)." (PMID 41720764, 2026). "For example, miR-491 was found to attenuate CSCs properties by suppressing GIT-1/NF-κB-mediated EMT in hepatocellular carcinoma (HCC)." (PMID 34685504, 2021).
lymph node metastasis (4 papers, 2015 to 2019). "They usually bind to GIT1, and the elevation of GIT1 correlated with lymph node metastasis and thus tumor grade." (PMID 30901831, 2019). "It has been shown that GIT1 levels were positively correlated with lymph node metastasis in oral squamous cell carcinoma." (PMID 26462147, 2015). "Finally, we examined the relationship between GIT1 expression and the clinicopathologic characteristics of NSCLC and found that a high level of GIT1 was positively correlated with lymph node metastasis (P = 0.023) and early recurrence (P = 0.036)." (PMID 26462147, 2015).
oral squamous cell carcinoma (4 papers, 2015 to 2022). "Silencing GIT1 inhibits the metastasis of oral squamous cell carcinoma cells." (PMID 34663332, 2021).
attention deficit-hyperactivity disorder (3 papers, 2018 to 2025). A disorder characterized by a marked pattern of inattention and/or hyperactivity-impulsivity that is inconsistent with developmental level and clearly interferes with functioning in at least two settings (e.g. at home and at school). "Some other reports also showed GIT1 knockdown leads to neuropsychiatric disorders such as depression and attention deficit hyperactivity disorder (ADHD)." (PMID 41255384, 2025). "GIT1, a novel interactor of B9D1 is associated with attention deficit hyperactivity disorder and MME, a novel interactor of SPAG1with Alzheimer’s disease." (PMID 32973177, 2020). "Mice lacking GIT1 have been proposed as a model for attention deficit-hyperactivity disorder, due to alterations in basal locomotor activity as well as paradoxical locomotor suppression by the psychostimulant amphetamine." (PMID 29554125, 2018).
Intellectual disability (3 papers, 2016 to 2021). "Instead, GIT1-deficient mice exhibit profound learning and memory defects and reduced synaptic structural plasticity, consistent with an intellectual disability phenotype." (PMID 29554125, 2018). "Based on interactions with α-PIX and PAK3, known human X-linked intellectual disability genes, GIT1 was suggested to regulate cognitive function through regulation of synaptic plasticity, and experiments in primary neurons have indicated synaptic roles." (PMID 29554125, 2018). "In contrast, multiple learning and memory defects have been observed here and in other studies using distinct GIT1-knockout lines, consistent with a predominant intellectual disability phenotype related to altered synaptic structural plasticity." (PMID 29554125, 2018). "Because the GIT1 partner α-PIX and its partner PAK3 are known human X-linked intellectual disability genes, it was expected that GIT1 might be important for learning and memory." (PMID 29554125, 2018).
medullary thyroid carcinoma (3 papers, 2020 to 2021). "GIT1 is targeted by miR-149-5p to suppress the invasion and proliferation of medullary thyroid carcinoma cells." (PMID 33258389, 2021).
melanoma (3 papers, 2019 to 2025). A malignant, usually aggressive tumor composed of atypical, neoplastic melanocytes. "The rescue studies demonstrated that UBTF facilitated melanoma cell proliferation, cell cycle progression, and inhibited apoptosis through promoting GIT1 transcription." (PMID 34663332, 2021). "ChIP-RT-PCR assay also confirmed that UBTF bound to the promoter (Primer 6) of GIT1 in melanoma cells." (PMID 34663332, 2021). "It was verified that UBTF promoted GIT1 transcription in melanoma cells through binding to the promoter region of GIT1." (PMID 34663332, 2021). "Our study demonstrates that UBTF promotes melanoma cell proliferation and cell cycle progression by promoting GIT1 transcription, thereby activating MEK1/2-ERK1/2 signalling pathways." (PMID 34663332, 2021). "To explore the possible molecular mechanism of UBTF regulation in melanoma, we fulfilled bioinformatics predicting, ChIP-qRT-PCR and reporter gene assay, through which we ascertained GIT1 as UBTF targeting gene." (PMID 34663332, 2021). "The qRT-PCR results also showed that UBTF mRNA expression was remarkably positively correlated with GIT1 mRNA expression in melanoma (n = 66, r = 0.4313, p < 0.001, Pearson’s correlation)." (PMID 34663332, 2021). "MTT and colony formation assays were used to investigate the effects of UBTF and GIT1 on melanoma cell proliferation." (PMID 34663332, 2021). "TCGA data showed that UBTF expression was positively related with GIT1 expression in human melanoma tissues (n = 469, r = 0.39, p < 0.001)." (PMID 34663332, 2021). "UBTF and GIT1 expressions in melanoma specimens and cell lines were examined by quantitative real-time PCR (qRT-PCR) and Western blot." (PMID 34663332, 2021). "The GIT1 expression was significant higher in metastatic melanoma tissues than in tumor and normal skin tissues (p < 0.001)." (PMID 34663332, 2021). "Cell viability assay showed that silencing UBTF inhibited melanoma cell multiplication, overexpressing GIT1 rescued the effect of UBTF siRNA-1 on cell growth (p < 0.01)." (PMID 34663332, 2021). "The qRT-PCR assay revealed that GIT1 mRNA expression was remarkably upregulated in 75.8% (50/66) of the melanoma tissues (p < 0.001)." (PMID 34663332, 2021). "It was demonstrated that UBTF promoted GIT1 expression in melanoma cells through binding to the promoter region of GIT1." (PMID 34663332, 2021). "UBTF promotes melanoma cell proliferation and cell cycle progression by facilitating GIT1 transcription, thereby activating MEK1/2-ERK1/2 signalling pathways." (PMID 34663332, 2021). "MTT assay showed that silencing GIT1 remarkably suppressed melanoma cell multiplication at 48 and 72 h after transfection (p < 0.01), while overexpressing GIT1 significantly facilitated melanoma cell growth (p < 0.01)." (PMID 34663332, 2021). "TCGA data showed that the GIT1 expression was markedly upregulated in melanoma tissues compared with normal skin tissues (p < 0.001)." (PMID 34663332, 2021). "Our data confirmed that UBTF facilitates melanoma cell proliferation and cell cycle progression by promoting GIT1 transcription, thereby activating MEK1/2-ERK1/2 signalling pathways." (PMID 34663332, 2021). "The high GIT1 expression was correlated to the overall survival and disease specific survival of melanoma patients (p < 0.01)." (PMID 34663332, 2021). "In the present study, we found that GIT1 expression was upregulated in melanoma." (PMID 34663332, 2021). "Furthermore, the high GIT1 mRNA expression was relevant to melanoma thickness, lymph node metastasis and initial stage." (PMID 34663332, 2021). "GIT1 promoted melanoma cell proliferation and suppressed apoptosis in vitro." (PMID 34663332, 2021). "Overexpression of GIT1 eliminated the effects of silencing UBTF on melanoma cells." (PMID 34663332, 2021). "The findings demonstrated UBTF as a transcriptional regulator of GIT1 in human melanoma cells." (PMID 34663332, 2021). "The GIT1 protein expression was observably increased in melanoma tissues." (PMID 34663332, 2021).
melanoma (continued). "UBTF expression was positively related with GIT1 expression in human melanoma tissues." (PMID 34663332, 2021). "Furthermore, GIT1 overexpression promoted melanoma cell growth and suppressed apoptosis." (PMID 34663332, 2021). "Interestingly, few gene pairs were specific to cell lineage, with the notable exception of GIT1|GIT2 which was a hit in 12 cell lines, but never in a melanoma line." (PMID 40968372, 2025).
Sepsis (3 papers, 2021 to 2025). Sepsis is defined as life-threatening organ dysfunction caused by a dysregulated host response to infection. "We speculated that the effect of miR-122-5p on sepsis may be associated with the modulation of GIT1." (PMID 34002676, 2021). "Although there are limitations in identifying the possible pathogenic mechanisms of myocardial injury in sepsis, the discovery of the Nrf-2 signaling pathway in relation to miR-122-5p/GIT1 axis contributes to our better understanding of the pathogenesis of septic myocardial injury." (PMID 34002676, 2021). "In line with the previous studies, we confirmed that GIT1 deficiency partially reversed miR-122-5p inhibition-mediated protective effect on sepsis as evidenced by increased cell apoptosis, triggered ROS production, elevated LDH content, enhanced TNF-α level, and reduced SOD activity." (PMID 34002676, 2021). "Inhibiting miR-122-5p can alleviate sepsis-induced myocardial injury by targeting GIT1 to inhibit inflammation, oxidative stress and apoptosis." (PMID 37635258, 2023). "Our results demonstrated that GIT1 was a target gene of miR-122-5p and was low-expressed in sepsis." (PMID 34002676, 2021). "We further analyzed whether the effect of miR-122-5p/GIT1 axis on sepsis is regulated by the Nrf-2 signaling pathway." (PMID 34002676, 2021). "Taken together, our data suggest that inhibition of miR-122-5p may mitigate sepsis-triggered myocardial injury through inhibiting inflammation, oxidative stress and apoptosis via targeting GIT1, which provides a possible therapeutic target for sepsis." (PMID 34002676, 2021). "Also, GIT1 was down-regulated in response to sepsis, and it might be a target gene of miR-122-5p." (PMID 34002676, 2021).
Anxiety (2 papers, 2018 to 2025). Intense feelings of nervousness, tension, or panic often arise in response to interpersonal stresses. "We previously reported that GIT1 knockout mice exhibit numerous normal behaviors related to anxiety, depression and gross locomotor function, but exhibit very poor memory performance after fear conditioning." (PMID 29554125, 2018). "We previously showed that older (8 month old) adult GIT1-KO mice had relatively normal locomotor activity in the open field during a screen for anxiety-like behavior." (PMID 29554125, 2018).
breast tumours (2 papers, 2017 to 2022). "GIT1 knockdown in ER(-) breast tumour cells increased signalling downstream of Notch and activity of aldehyde dehydrogenase, a predictor of poor clinical outcome." (PMID 35318302, 2022). "GIT1 also plays a key role in controlling breast tumour growth in vitro and in vivo through its regulation of Notch signalling." (PMID 35318302, 2022). "Knockdown of GIT1 in ER(−) breast tumour cells elevates Notch activity and increases ALDH1+ cell count." (PMID 35318302, 2022). "Our results support the notion that, at least in ER+ breast tumours, down-regulation of GIT1 in lymph node metastases is a sign of poor prognosis." (PMID 29862012, 2017). "We observed a significant reduction in GIT1 expression in lymph node metastasis compared to matched primary breast tumours." (PMID 29862012, 2017). "In this study, we identified GIT1 as a Notch-interacting protein in breast tumour cells." (PMID 35318302, 2022). "Our data provide a reasonable explanation for the observed higher Notch activity in ER(−) breast tumours: the lower protein levels of GIT1 in ER(−) breast tumours not only serve as a prognostic biomarker but also lead to elevated Notch nuclear localization and activity." (PMID 35318302, 2022). "GIT1 directly interacts with the Notch ICD and regulates the nuclear entry of the Notch ICD in ER(−) breast tumour cells." (PMID 35318302, 2022).
microcephaly (2 papers, 2021). A congenital or acquired developmental disorder in which the circumference of the head is smaller than normal for the person's age and sex. "Additional phenotypes reported in mice and flies upon GIT1 deletion, such as microcephaly, reduced neuronal size or hyperactivity, might also be related to mTOR modulation." (PMID 34787081, 2021).
osteoarthritis (2 papers, 2019 to 2021). A noninflammatory degenerative joint disease occurring chiefly in older persons, characterized by degeneration of the articular cartilage, hypertrophy of bone at the margins and changes in the synovial membrane. "According to a recent study, KLF3-AS1 promotes cartilage repair and chondrocyte proliferation by impairing the miR-206-mediated inhibition of GIT1 in osteoarthritis." (PMID 34621793, 2021). "In osteoarthritis, KLF3-AS1 derived from hMSCs can facilitate chondrocyte by acting as a ceRNA to bind with miR-206 and regulate the expression of GIT1." (PMID 31847890, 2019).
osteoporosis (2 papers, 2017 to 2020). A condition of reduced bone mass, with decreased cortical thickness and a decrease in the number and size of the trabeculae of cancellous bone (but normal chemical composition), resulting in increased fracture incidence. "GIT1 is a key regulator of bone mass in vivo by regulating osteoclast function, and miR195 might affect osteoporosis pathology by controlling chondrocyte differentiation and bone mass regulation." (PMID 32802851, 2020). "Furthermore, a major function of GIT1 is to regulate cytoskeletal dynamics to facilitate cell spreading and spatial targeting, and GIT1 is a potential target for the treatment of osteoporosis." (PMID 28754105, 2017).